CHUK (component of inhibitor of nuclear factor kappa B kinase complex)
Diseases named in the same sentence as CHUK in open-access papers (continued):
Sharing a sentence is not in itself a finding about the gene and the disease.
esophageal squamous cell carcinoma (2 papers, 2021 to 2024). Esophageal squamous cell carcinoma (ESCC) is a type of esophageal carcinoma (EC) that can affect any part of the esophagus, but is usually located in the upper or middle third. "The study on an animal model showed that the reduction of the CHUK gene was associated with chronic fungal infection and the subsequent development of esophageal squamous cell carcinoma." (PMID 39337357, 2024). "Lower expression levels of CHUK, IKBKB, and IKBKG in stomach adenocarcinoma and IKBKB in esophageal squamous cell carcinoma correlate with shorter overall survival." (PMID 39337357, 2024).
gastric adenocarcinoma (2 papers, 2024 to 2025). "For instance, in stomach adenocarcinoma, CHUK and IKBKB are upregulated in higher histological grades and greater lymph node infiltration." (PMID 39337357, 2024).
Alzheimer disease (1 paper, 2020). A progressive, neurodegenerative disease characterized by loss of function and death of nerve cells in several areas of the brain leading to loss of cognitive function such as memory and language. "In RT-PCR assays, pre-treatment with GLE decreased mRNA expression of CHUK, NFκB1/p150, and IKBKE (NFƙB signaling), which may be associated with the neuropathology of Alzheimer’s disease." (PMID 32480240, 2020).
breast adenocarcinoma (1 paper, 2025). "Mutations in the NOD1/2 signaling pathway and in DNA binding transcription factor activity, affecting genes such as MAP3K7, UBE2N, IKBKG, CHUK, and IKBKB, occurred late in breast adenocarcinoma and ovarian adenocarcinoma." (PMID 39868264, 2025).
Hepatic steatosis (1 paper, 2023). Steatosis is a term used to denote lipid accumulation within hepatocytes. "In humans, CHUK polymorphisms are associated with hepatic steatosis." (PMID 36837811, 2023).
hepatitis C virus infection (1 paper, 2019). A viral infection caused by the hepatitis C virus. "CHUK gene is also named IKKA gene, and IKKα is normally an activator of the transcription factor nuclear factor-κB, and it leads to potent activation of SREBP-mediated lipogenesis in the context of hepatitis C virus infection." (PMID 31419940, 2019).
metabolic syndrome (1 paper, 2023). A cluster of metabolic risk factors for CARDIOVASCULAR DISEASES and TYPE 2 DIABETES MELLITUS. "Thus, herein, we constructed a mRNAs (DDX58, NFκB1& CHUK)—(miR-1976) panel linked to metabolic syndrome and pancreatic cell dysfunction as well as be enrolled in the cGAS-STING pathway via in silico data analysis." (PMID 36915161, 2023).
pneumonitis (1 paper, 2023). An inflammatory process affecting the lung parenchyma. "Furthermore, protein–protein interaction analysis showed that RELA was interrelated with CHUK, ROCK1, and ROCK2, and we chose RELA as a candidate EV protein to predict symptomatic pneumonitis." (PMID 37614219, 2023).
toxoplasmosis (1 paper, 2022). A parasitic disease contracted by the ingestion or fetal transmission of toxoplasma gondii. "Interestingly, CHUK was one of the candidate genes in the toxoplasmosis pathway which highlights the role of CHUK as an important modulator of the inflammatory response." (PMID 35464478, 2022). "In addition to the TNF pathway, we detected enrichment of candidate genes involved in the toxoplasmosis (TGFβ2/CHUK/CIITA/SOCS1) pathway in the tolerant animals." (PMID 35464478, 2022). "In addition, the TNF-signaling (bta04668; TRAF5/CREB5/CASP7/CHUK) and the toxoplasmosis (bta05145; TGFβ2/CHUK/CIITA/SOCS1) pathways were significantly enriched." (PMID 35464478, 2022).
Trichiasis (1 paper, 2019). Inversion and rubbing of the eyelashes against the globe of the eye. "The upregulation of pro-inflammatory mediators and cell markers (CCL2, CCL3, CXCL5,IL1B, IL6, CHUK, FUT4 andPTPRC) is indicative of higher levels of inflammation and leukocyte infiltration in the conjunctival tissue of patients who developed ECA following trichiasis surgery." (PMID 37426632, 2019).
tumor (132 papers, 2003 to 2026). "Our analyses of somatic mutations were consistent with a tumor suppressive role for the CHUK gene, which had a high frequency of truncating mutations and somatic alterations affected both alleles in most tumors." (PMID 34272401, 2021). "Other studies in a mouse model have shown that the presence of CHUK was important in tumor initiation and proliferation in colon cancer." (PMID 39337357, 2024). "We also found a reduction in the expression of CHUK (IKKα) and similar regulatory proteins of NF-κB in the tumor cells in comparison to normal." (PMID 30225173, 2018). "Several members of the canonical NF-κB pathway were in the top list, including RELA, NFKB1, CHUK, IKBKB, IKBKG, and REL, indicating that the canonical NF-κB pathway was closely associated with immune-related DEGs in tumour serum-cultured DCs." (PMID 28350008, 2017). "CHUK/IKKα has emerged as a novel tumor suppressor in several organs of humans and mice." (PMID 33808757, 2021). "The CHUK gene mRNA level was positively correlated with tumor purity (lack of infiltrating cells) for ESCA and STAD tumors, but significant connections were only noted in ESCA." (PMID 39337357, 2024). "Thus, CHUK, IKBKB gene products, and co-chaperones FKBP5 (FKBP51), TSC1, and TSC2 interact with Hsp90 and behave like tumor suppressors, while AKT1 shows oncogenic behavior and is involved in the enhanced activity of many signaling pathways." (PMID 39337357, 2024). "The results of this integrative cBioPortal analysis suggest that genes AKT3, CHUK and PTEN behave like tumor suppressors, while AKT1, AKT2, EGFR, and PIK3AP1 show oncogenic behavior and are involved in enhanced activity of the EGFR-PI3K-AKT-mTOR signaling pathway." (PMID 34209611, 2021). "For spleens from tumor bearing old mice majority of the upstream regulators are either interferons (IFNγ, IFNα, IRF3, IRF7, and IFNA2) or are related to the immune system (IKBKB, CHUK, NFκB, NFκBIA, STAT3, and mir-21) and are predicted to be up-regulated." (PMID 26497558, 2015). "The activation of three stringent UPRs related to DNA damage pathways in both GL261 and LLC tumors (CHUK/IKBKA, IKBKB and JUN) or in all three tumor models (CHUK, IKBKB) may reflect the cytotoxic responses common to CPA treatment in all three tumor models." (PMID 27515027, 2016).
cancer (104 papers, 2009 to 2025). A tumor composed of atypical neoplastic, often pleomorphic cells that invade other tissues. "Downregulation of IKKα in human cancers is associated with the DNA methylation of the CHUK gene." (PMID 37686574, 2023). "CHUK and NFKB1 are engaged in a complex crosstalk linked to cancer progression and drug resistance due to their ability to activate inflammatory responses and promote cell survival." (PMID 40650045, 2025). "Nevertheless, CHUK plays a minor role in maintaining the viability of autophagy-dependent cancer cells, because siRNA targeted against the CHUK gene (siCHUK) suppressed CHUK expression but did not affect proliferation of either A375 or HFF1 cells." (PMID 36803256, 2023). "Patients with altered CHUK gene signatures had a statistically significant reduced cancer-specific survival outcome (p = 0.026)." (PMID 35173303, 2022). "The NFkB pathway, a regulator of immune and inflammatory responses, also implicated in cancer cell proliferation, survival, angiogenesis and plasticity, was downregulated at the level of NFkB (NFKB1) itself and IKK kinase (CHUK)." (PMID 39495207, 2024). "Only in N0, DNA (excision-) repair (involved genes: CDKN1A, PPM1D, and DDB2) was predicted to be a downstream function, while molecular networks in N2+ were associated with cancer, as well as injury and abnormalities (among others, downregulation of MSH6, CCNE2, and CHUK)." (PMID 36068491, 2022). "This revealed a significant positive correlation between IKKα (gene symbol: CHUK) and MYC expression in prostate-, as well as other cancer types implying a functional link between IKKα expression and c-Myc levels in humans in vivo." (PMID 33461590, 2021). "We found that according to the KEGG enrichment of the common DEGs deregulated upon SOX2OT inhibition; the pathways related to cancer (Kegg: 05200) is one of the most significant enriched pathway (p-value = 0.009285) with 6 genes (HIF1A, HRAS, CHUK, PIK3CA, CDK2, VHL)." (PMID 30202240, 2018).
infection (49 papers, 2004 to 2025). The state of being infected such as from the introduction of a foreign agent such as serum, vaccine, antigenic substance or organism. "We conclude that IFNA1, IRF3, CXCL8, CXCL10, IFNB1, and CHUK are the key hub genes involved in the H5N1 human infection, which makes a major contribution towards the inflammation or cytokine storm leading to the prognosis of the disease and critical clinical outcomes." (PMID 37515084, 2023). "Lastly, The Ser/Thr kinase COT, CHUK (Iκκ-A), NF-κB1A (IκB), and NF-κB (p105 and p100), all significantly phosphorylated within 4-8 h of infection with S. Enteritidis, but all were found to be no different than non-infected control levels by 24 h." (PMID 35846741, 2022).
adenocarcinoma (2 papers, 2019 to 2024). A common cancer characterized by the presence of malignant glandular cells. "CHUK gene expression was significantly higher in the group of patients with the tubular-intestinal-adenocarcinoma subtype than in the subgroup with diffuse adenocarcinoma of STAD cancer (p = 0.0103)." (PMID 39337357, 2024).
CHUK also shares sentences with these, for which no sentence is quoted: pancreatic cancer (15 papers); skin tumors (13); viral infection (13); skin cancer (11); Insulin resistance (10); gastric cancer (9); hepatocellular carcinoma (8); liver cancer (8); nasopharyngeal carcinoma (8); glioblastoma (7); ovarian carcinoma (7); Sepsis (7); asthma (6); autoimmune disease (5); chondrosarcoma (5); colon carcinoma (5); diabetes (5); multiple myeloma (5); papilloma (5); rheumatoid arthritis (5); Arthritis (4); basal cell carcinoma (4); cervical cancer (4); kidney diseases (4); liver fibrosis (4); pancreatitis (4); Stroke (4); bacterial infection (3); cholestasis (3); ectodermal dysplasia (3).
A further 147 diseases each share a sentence with CHUK in 3 papers or fewer.